USP13 (ubiquitin specific peptidase 13)
Diseases named in the same sentence as USP13 in open-access papers (continued):
Sharing a sentence is not in itself a finding about the gene and the disease.
CNS tumors (3 papers, 2019 to 2024). "Next, an in vivo study was conducted with a intracerebroventricular injection of ZIKV in BALB/c nude mice after period of CNS tumor establishment (1 to 2 weeks for DAOY, USP13-MED and USP7-ATRT cell lines)." (PMID 39347716, 2024). "The two embryonal CNS tumor cell lines, USP7 and USP13, formed the largest and most numerous tumoroids, while the GBM cell line U343-MG generated fewer and denser structures." (PMID 39599878, 2024). "The therapeutic potential of miR‐367 was further confirmed in vivo, in an orthotopic xenograft model of aggressive embryonal CNS tumors initiated by OCT4A‐overexpressing cells (Daoy, USP13‐MED, or USP7‐ATRT) in Balb/C nude mice." (PMID 31402560, 2019).
adenocarcinoma (1 paper, 2023). A common cancer characterized by the presence of malignant glandular cells. "Therefore, in the oncogenic KRAS-mediated transformed club cells, USP13 seems to prevent those club cells from adopting an AT2-like adenocarcinoma identity, instead switching the fate of cells to squamous cell traits." (PMID 38093367, 2023). "To determine whether USP13 can alter the lineage characteristics of advanced lung tumors through MYC, we overexpressed USP13 in the murine adenocarcinoma KP primary cell line and human LUAD cell lines followed by immunoblotting for squamous markers, such as SOX2, p40, or CK5." (PMID 38093367, 2023).
infectious disease (1 paper, 2017). A disorder directly resulting from the presence and activity of a microbial, viral, or parasitic agent in humans. "Our study contributes to the complicated regulatory molecular mechanisms of antiviral responses and provides USP13 as a potential target for future adjuvant or medicine design for infectious diseases." (PMID 28534493, 2017).
inflammation (1 paper, 2019). Aberrant reaction of the microcirculation characterized by movement of fluid and leukocytes from the blood into extravascular tissues. "The LentiSigirr transduction effectively dampened the enhanced LPS-induced lung inflammation phenotype observed in Usp13−/− animals, with reduced cellular infiltration and neutrophils, TNF-α, and IL-1β." (PMID 31204278, 2019).
kidney diseases (1 paper, 2023). "However, the role of USP13 in other kidney diseases is still obscure." (PMID 37452432, 2023).
metabolic disorders (1 paper, 2024). "However, the study involving USP13 function in metabolic disorders and NAFLD remains limited." (PMID 39033101, 2024).
movement disorder (1 paper, 2022). Neurological conditions resulting in abnormal voluntary or involuntary movement, which may impact the speed, fluency, quality and ease of movement. "When taken together, these findings suggest that DUBs, including USP13, may play a critical role in the pathology of several movement disorders." (PMID 35897705, 2022).
neurological diseases (1 paper, 2023). "Together, these findings suggest a previously unappreciated role and mechanism of USP13 in Wallerian degeneration, and increase of USP13 may enhance the ARM-TIR lock and attenuate SARM1 activation in nerve injury and other neurological diseases involving axon degeneration." (PMID 39872893, 2023).
vascular disorder (1 paper, 2026). A general term used to describe any disease affecting blood vessels]. "In conclusion, our findings elucidate the role of USP13 in vascular remodeling under pressure overload, suggesting that targeting USP13 may offer therapeutic potential for pathological vascular disorders." (PMID 41484066, 2026).
USP13 also shares sentences with these, for which no sentence is quoted: chronic myelogenous leukemia (2 papers); esophageal cancer (2); idiopathic pulmonary fibrosis (2); neuroblastoma (2); ovarian serous carcinoma (2); age (1); amyotrophic lateral sclerosis (1); bladder urothelial cancer (1); cervical disease (1); diffuse large B-cell lymphoma (1); endometrium carcinoma (1); esophageal squamous cell carcinoma (1); frontotemporal dementia (1); head and neck cancer (1); head and neck squamous cell carcinoma (1); lupus nephritis (1); nonalcoholic fatty liver disease (1); pancreatic adenocarcinoma (1); progressive multifocal leukoencephalopathy (1); renal cell carcinoma (1); rhabdoid tumor (1); thyroid tumor (1); triple-negative breast carcinoma (1); uterine corpus endometrial carcinoma (1).